ERLIN1 (ER lipid raft associated 1)
Description:
Component of the ERLIN1/ERLIN2 complex which mediates the endoplasmic reticulum-associated degradation (ERAD) of inositol 1,4,5-trisphosphate receptors (IP3Rs). Involved in regulation of cellular cholesterol homeostasis by regulation the SREBP signaling pathway. Binds cholesterol and may promote ER retention of the SCAP-SREBF complex. (Microbial infection) Required early in hepatitis C virus (HCV) infection to initiate RNA replication, and later in the infection to support infectious virus production.
Synonyms: C10orf69; KE04; KEO4; SPFH1; Erlin-1; SPG62
Tractability: Antibody: UniProt predicts a signal peptide or a membrane-spanning region. PROTAC: ubiquitination databases record sites on it; its protein half-life has been measured.
Gene: Protein-coding gene on chromosome 10 (100,150,094 to 100,186,033, reverse strand). Ensembl gene ENSG00000107566.
Subcellular location: Endoplasmic reticulum membrane
Subcellular location (Human Protein Atlas): Endoplasmic reticulum
Pathways (Reactome):
Disease: Defective CFTR causes cystic fibrosis
Immune System: AMPK-induced ERAD and lysosome mediated degradation of PD-L1(CD274)
Transport of small molecules: ABC-family protein mediated transport
Gene Ontology:
Molecular function: cholesterol binding; protein binding; ubiquitin protein ligase binding
Biological process: ERAD pathway; negative regulation of cholesterol biosynthetic process; negative regulation of fatty acid biosynthetic process; regulation of cholesterol biosynthetic process; SREBP signaling pathway
Cellular component: endoplasmic reticulum; endoplasmic reticulum membrane; protein-containing complex; membrane raft
Genetic constraint (gnomAD): Loss-of-function variants: 7 observed, 12.53 expected, observed/expected ratio (o/e) 0.56, 90% interval 0.32 to 1.05. The upper end of that interval is the gene's LOEUF score, 1.05, which puts it in group 4 of 6, group 1 being the genes least tolerant of losing a copy. Missense variants: 91 observed, 140.87 expected, observed/expected ratio (o/e) 0.65, 90% interval 0.54 to 0.77. Synonymous variants: 66 observed, 55.35 expected, observed/expected ratio (o/e) 1.19, 90% interval 0.98 to 1.46.
Gene-disease validity (ClinGen):
ClinGen rates the evidence that ERLIN1 causes each of these diseases.
hereditary spastic paraplegia 62 (autosomal recessive): Definitive.
Homologues: Orthologues: chimpanzee ERLIN1 (100% identical), macaque ERLIN1 (99% identical), rabbit ERLIN1 (98% identical), guinea pig ERLIN1 (97% identical), mouse Erlin1 (96% identical), dog ERLIN1 (95% identical), rat Erlin1 (95% identical), zebrafish erlin1 (76% identical), tropical clawed frog erlin1 (73% identical), Caenorhabditis elegans erl-1 (57% identical). Paralogues in human: ERLIN2 (72% identical).